CCL25 (C-C motif chemokine ligand 25)
Diseases named in the same sentence as CCL25 in open-access papers (continued):
Sharing a sentence is not in itself a finding about the gene and the disease.
periodontitis (5 papers, 2017 to 2026). An acute or chronic inflammatory process that affects the tissues that surround and support the teeth. "In patients with aggressive periodontitis, reduced levels of DNA methylation in the promoters of CCL25 and IL17C compared to healthy controls have been identified." (PMID 33256844, 2020). "A decrease in methylation level was found in promoter regions of IL17C and CCL25 in periodontitis patients indicating an increase in gene expression." (PMID 29201597, 2017). "In addition to classical pro-inflammatory cytokines, our cytokine array analysis revealed significant upregulation of several chemokines in ligature-induced periodontitis, including thymus chemokine (CCL25), CINC-1 (CXCL1), and CINC-2α/β (CXCL3)." (PMID 41583507, 2026).
atherosclerosis (4 papers, 2017 to 2024). A disease characterized by the build-up of fatty material and calcium deposition in the arterial wall resulting in partial or complete occlusion of the arterial lumen. "Surprisingly, some markers of atherosclerosis (fractalkine/CX3CL1, CCL8, M-CSF, HGF), T-cell development/activation (CD40L, IL-7, CCL25, IL-2RB, IL-15RA, CD6) and angiogenesis (VEGF-A) were significantly increased only in AD." (PMID 28821884, 2017).
autoimmune disease (4 papers, 2006 to 2025). A disorder resulting from loss of function or tissue destruction of an organ or multiple organs, arising from humoral or cellular immune responses of the individual to their own tissue constituents. "CCR9/CCL25 forms a signaling axis critical for T-cell homing to the small intestine that has been implicated in gut immune surveillance, IBD, gut innate immunity, and autoimmune disorders." (PMID 40894167, 2025). "A review described the involvement of CCL25/CCR9 in various pathological processes, such as inflammatory diseases, autoimmune diseases, metabolic disorders, and tumorigenesis." (PMID 39411316, 2024).
leukemia (4 papers, 2018 to 2022). A malignant (clonal) hematologic disorder, involving hematopoietic stem cells and characterized by the presence of primitive or atypical myeloid or lymphoid cells in the bone marrow and the blood. "Many chemokine axes such as CXCL12/CXCR4 and CCL25/CCR9 have been proved to play important roles in leukemia microenvironment and further affect ALL outcomes." (PMID 33743810, 2021). "Therefore, inhibiting CCL25/CCR9 may be a potential therapeutic strategy for treating leukemia patients, and it is of great significance to further explore the role of CCL25/CCR9 in leukemia." (PMID 33743810, 2021). "Our studies have shown that CCL25 induces MOLT4 cells (human T-ALL cell line with naturally high expression of CCR9) polarization and microvilli absorption to participate in leukemia infiltration and trafficking via the RhoA-Rock-MLC and ezrin pathway." (PMID 33743810, 2021).
allergic reaction (3 papers, 2015 to 2023). "In a model of allergic reaction, IL-17+ γδTc expressed α4β7 that enabled their mobilization by CCL25 in inflamed tissue, which in turn modulated IL-17 levels." (PMID 29593745, 2018). "Blocking α4β7 in vivo prevented the migration of IL-17+ γδTc but not αβTc into mouse pleura, and also blocked transmigration of γδTc across VCAM-1- and MadCAM-1-expressing endothelium toward CCL25 or cell-free pleural washes from mice in whom an allergic reaction had been induced." (PMID 29593745, 2018). "Moreover, CCL25 is involved in the chemotaxis of T lymphocytes, participating in a variety of physiological and pathological processes, including immune cell development, differentiation, and allergic diseases." (PMID 38274820, 2023).
Arthritis (3 papers, 2014 to 2024). Inflammation of a joint. "CCL25 should exacerbate arthritis via these effects in addition to the inflammatory cell recruitment." (PMID 25248373, 2014).
autoimmune conditions (3 papers, 2010 to 2025). "Moreover, the same authors reported that CCL25-deficient mice showed autoimmunity in some organs, which was similar to the phenotype of Aire-deficient mice." (PMID 38022666, 2023). "Therefore, in addition to detailed characterization, an important future study should address whether CCL25-expressing mTECs are critical to suppress onset of autoimmunity." (PMID 38022666, 2023).
Chronic colitis (3 papers, 2011 to 2025). A chronic inflammatory disease of the large intestine (colon, cecum and rectum). "CCR9/CCL25 interactions have protection against large intestinal inflammation in chronic colitis." (PMID 34490243, 2021). "Further investigation will determine whether CCL25/CCR9 interactions play a role in DSS chronic colitis." (PMID 21283540, 2011).
endometriosis (3 papers, 2014 to 2025). The growth of functional endometrial tissue in anatomic sites outside the uterine body. "Elevated levels of estrogen and thymus-expressed chemokine (TECK/CCL25) lead to an increase in Tregs, which in turn reduces immune surveillance in endometriosis patients." (PMID 40508002, 2025). "The use of anti-CCL25 or anti-CCR9 antibodies may also provide an effective therapeutic modality for patients with endometriosis." (PMID 33803806, 2021). "Furthermore, elevated PF levels of chemokine CCL25 were found in patients with endometriosis and correlated with the stage of the disease and increased M-MDSC migration into the peritoneal cavity." (PMID 33803806, 2021).
gastric cancer (3 papers, 2019 to 2023). A primary or metastatic malignant neoplasm involving the stomach. "The results showed that CCL25 was significantly enriched in “B cell receptor signalling pathway”, “Colorectal cancer”, “Gastric cancer”, “IL-17 signalling pathway” and “Human T-cell leukaemia virus 1 infection”." (PMID 37587523, 2023).
ileitis (3 papers, 2011 to 2016). "Interference with the CCR9/CCL25 axis has been shown to improve disease symptoms and tissue inflammation in mouse models of ileitis such as the SAMP-1/Yit model and the TNF-ΔARE model." (PMID 26457007, 2015). "Blockade of CCR9 or CCL25 does not attenuate inflammation during the late stages of chronic murine ileitis." (PMID 27424033, 2016). "Indeed, targeting the CCR9/CCL25 axis has been shown to be of benefit in the TNF-ΔARE and SAMP-1/YIT models of ileitis." (PMID 26457007, 2015).
Obesity (3 papers, 2019 to 2025). Accumulation of substantial excess body fat. "Second, five proteins (CCL25, GRIA4, HBEGF, NPPA and RETN) were also considered because they have been reported to be associated with obesity." (PMID 35879730, 2022). "MVMR further revealed that CXCL9, TNFSF12 (all-grade), and CCL25 (high-grade) exert BMI-independent effects, implicating direct immunomodulatory pathways rather than obesity-related inflammation." (PMID 40722787, 2025). "In addition, the proteins CCL25, GRIA4, HBEGF, NPPA and RETN, which are affected by RNAm-SNPs, have been reported to be related to obesity." (PMID 35879730, 2022).
Sepsis (3 papers, 2015 to 2024). Sepsis is defined as life-threatening organ dysfunction caused by a dysregulated host response to infection. "The involvement of CCL25 in γδ T cell migration towards inflamed lungs during sepsis was also investigated by us, since CCL25 has been shown to attract IL-17+ γδ T cells into inflamed airways." (PMID 26037291, 2015). "Subsequent elevation of the genes encoding the inflammatory chemokines such as CCL16, CCL25 and CXCL6, and cytokines such as IL-2, IL-8 and IFNG in concert with delayed activation of the coagulation system are the typical signatures of sepsis." (PMID 27003632, 2016). "The association between higher AF and lower levels of CCL20, CCL23 and CCL25 in infant plasma, and lower plasma levels in infants who did not develop sepsis support our hypothesis that AF may have protective properties." (PMID 38001236, 2024). "Infants who developed sepsis had higher levels of the proteins CCL20, CCL23 and CCL25 in infant plasma week 4 compared to infants who did not." (PMID 38001236, 2024).
Cirrhosis (2 papers, 2019 to 2022). A chronic disorder of the liver in which liver tissue becomes scarred and is partially replaced by regenerative nodules and fibrotic tissue resulting in loss of liver function. "ALD-cirrhosis was associated with IL-6, CCL27 and G-CSF and NAFLD-cirrhosis with LIF and CCL25." (PMID 36230823, 2022). "The results revealed the significant diagnostic values of PF4 and PPBP in cirrhotic HCC, and CCL19, CCL25 in non-cirrhotic HCC, while no significant diagnostic values of CNR1 in HCC with or without cirrhosis were found." (PMID 31346321, 2019). "The serum levels of CCL25 and CCL11 were decreased in HCV cirrhosis, in comparison to the other cirrhotic groups but not to healthy controls." (PMID 36230823, 2022).
colorectal cancer (2 papers, 2023). A primary or metastatic malignant neoplasm that affects the colon or rectum. "In addition, six homeostatic chemokines, CXCL12, CCL1, CCL20, CCL25, CCL27, and CXCL11, were upregulated in the peripheral blood of patients with advanced colorectal cancer, which has also been reported to be associated with tumor progression." (PMID 37063892, 2023).
delirium (2 papers, 2025 to 2026). A disorder characterized by confusion; inattentiveness; disorientation; illusions; hallucinations; agitation; and in some instances autonomic nervous system overactivity. "Using delirium in the dementia-free UKB GWAS as outcome, ADAM8, CCL25, PILRA and LAYN lost their MR causal effect significance (FDR q > 0.05)." (PMID 41286463, 2026). "In our findings, we observed that elevated levels of CCL20, CCL25, and LIGHT were inversely associated with the likelihood of experiencing delirium." (PMID 40891141, 2025).
inflammatory liver diseases (2 papers, 2018 to 2026). "While Snapc2 and Ccl25 have been associated with liver disease, the function of Ppr36 has not been fully eluded even though it’s locus hosts variants associated with lipid metabolism by GWAS." (PMID 41544130, 2026). "For example, CCR9/α4β7 and CCL25/MadCAM for gut homing, CXCR3 and CXCL9-11 for inflammatory liver diseases and specifically, CCR9, αEβ7, CCL25/E-cadherin in AISC and PSC." (PMID 30027532, 2018).
liver fibrosis (2 papers, 2018 to 2022). "Recently, we reported that inhibition of the CCR9/CCL25 axis ameliorates acute hepatitis and liver fibrosis via regulation of hepatic macrophages." (PMID 35943802, 2022).
Sjögren syndrome (2 papers, 2020 to 2024). "CCR9 + T helper (Th) cells can induce Sjögren‐like symptoms in mice and both CCR9 + Th cells and their ligand CCL25 are increased in the salivary glands of primary Sjögren's syndrome (pSS) patients." (PMID 31733111, 2020).
squamous cell carcinoma (2 papers, 2014 to 2015). A carcinoma arising from squamous epithelial cells. "Interestingly, expression of both CCR9 and CCL25 was significantly higher in adenocarcinomas (ACs) compared to squamous cell carcinomas (SCCs) (p = 0.04, and p < 0.0001)." (PMID 25296976, 2014).
T-cell acute lymphoblastic leukemia (2 papers, 2017 to 2023). Acute lymphoblastic leukemia of T-cell origin. "LINC00853 has been reported to regulate the level of CC chemokine receptor 9 (CCR9) modulating the binding of CCR9 and CC chemokine ligand 25 (CCL25), which was involved in the process of the infiltration of T cell acute lymphoblastic leukemia." (PMID 37403034, 2023).
thymoma (2 papers, 2019 to 2024). A neoplasm arising from the epithelial cells of the thymus. "Real-time PCR analysis confirmed that CCL25 was upregulated; and MYC, GADD45B, TNFRSF12 downregulated in thymoma with MG." (PMID 30787364, 2019). "Significant increased expression of CCL25 was noticed in 80% (20/25) cases of thymoma with MG, while only one case of thymoma without MG that had overexpression of CCL25, which suggested that overexpression of CCL25 gene in thymoma might play a vital role in the pathogenesis of myasthenia gravis." (PMID 30787364, 2019). "By comparing transcriptome of thymoma with and without myasthenia gravis, we found that 5 genes (PNISR, CCL25, NBPF14, PIK3IP1 and RTCA) were upregulated more than 2-fold, and that more than 30 genes were downregulated more than 2-fold." (PMID 30787364, 2019).
thyroid cancer (2 papers, 2021 to 2024). "MCs also produce a broad spectrum of chemokines (CXCL8/IL-8, CCL25/TECK, CXCL10/IP-10, CXCL1/GRO-α), interleukins (IL-6), and other molecules (TNF-α) that are involved in the epithelial-to-mesenchymal transition (EMT) activation of thyroid cancer cells." (PMID 34204889, 2021).
triple-negative breast carcinoma (2 papers, 2020 to 2025). An invasive breast carcinoma which is negative for expression of estrogen receptor (ER), progesterone receptor (PR), and human epidermal growth factor receptor 2 (HER2). "More interestingly, intratumoral delivery of CCL25 can enhance PD-L1/PD-1 antibody therapy against triple-negative breast cancer by recruiting CCR9+ T cells." (PMID 33034614, 2020). "Moreover, intratumoral delivery of CCL25 enhanced the response to immunotherapy in triple-negative breast cancer by recruiting CCR9+ T cells." (PMID 41042869, 2025).
abscess (1 paper, 2018). An inflammatory process characterized by the accumulation of pus within a newly formed tissue cavity which is the result of a bacterial, fungal, or parasitic infection or the presence of a foreign body. "GO analysis with the unique differential promoters involved in Munro’s abscess formation revealed neutrophil and leukocyte chemotaxis as the highest enriched biological processes which include genes like HRH1, PDE4D, CCL25, AIF1, ADAM10, FFAR2, IL1B and TREM1." (PMID 30092825, 2018).
allergic asthma (1 paper, 2020). A asthma with a basis in a pathological type I hypersensitivity reaction. "Additionally, we found increased expression of CCR9 and its receptor CCL25, which are involved in inflammatory cell recruitment in early allergic asthma." (PMID 33329590, 2020). "The CCR9/CCL25 axis has been shown to induce cellular recruitment in early allergic asthma." (PMID 33329590, 2020).
autoimmune pancreatitis (1 paper, 2024). "A positive feedback loop consisting of IFN-alpha CXCL9, CXCL10, and CCL25 mediates experimental and human autoimmune pancreatitis." (PMID 39264798, 2024).
Candida infection (1 paper, 2012). "Of the chemoattractant mediators, several chemokines (Ccl25, Ccl27, Ccl28) and chemokine receptors (Ccr9, Ccr10, Cxcr5, Cxcr6, Cxcr7) associated with adaptive immunity were not induced after Candida infection." (PMID 22916017, 2012).
chronic kidney disease (1 paper, 2024). Impairment of the renal function secondary to chronic kidney damage persisting for three or more months. "We found increased levels of IL-6, IL-8, CD40, PDL-1, FGF-23, IL-15-RA, TGF-a, and CCL25 that persist at two months after LTA in IKF patients, consistent with current concepts of inflammation as a crucial pathophysiological mechanism in the development of chronic kidney disease." (PMID 39440014, 2024).
Coeliac disease (1 paper, 2025). "For Coeliac disease (CE), CCL25 (cytokine ligand 25) and CXCL9 (chemokine ligand 9) were on the top of the features list." (PMID 39897058, 2025).
colonic disease (1 paper, 2016). "In such a model, pro-inflammatory, effector mucosal CCR9+ T-cells would be preferentially recruited to the gut during the onset of active colonic disease in response to high levels of intestinal CCL25 expression." (PMID 26873648, 2016).
cutaneous melanoma (1 paper, 2019). A primary melanoma arising from atypical melanocytes in the skin. "Reference 97 to “Amersi, F.F.; Terando, A.M.; Goto, Y.; Scolyer, R.A.; Thompson, J.F.; Tran, A.N.; Faries, M.B.; Morton, D.L.; Hoon, D.S., Activation of CCR9/CCL25 in cutaneous melanoma mediates preferential metastasis to the small intestine." (PMID 31146450, 2019). "The correct reference is “Amersi, F.F.; Terando, A.M.; Goto, Y.; Scolyer, R.A.; Thompson, J.F.; Tran, A.N.; Faries, M.B.; Morton, D.L.; Hoon, D.S., Activation of CCR9/CCL25 in cutaneous melanoma mediates preferential metastasis to the small intestine." (PMID 31146450, 2019).
diabetes (1 paper, 2025). "In the analysis stratified by diabetes type, two biomarkers were positively associated with cognitive-affective symptoms in T2D (CCL25, GDNF)." (PMID 39799156, 2025). "This study demonstrates positive associations of CDCP-1, FGF-21, IL-8, IL-18, eotaxin/CCL11, MMP-10, TNFRSF9, CCL25 and IL-10RB with depressive symptoms in people with diabetes without interaction with diabetes type." (PMID 39799156, 2025). "Nine biomarkers were positively associated with depressive symptoms in the total sample (CCL11/eotaxin, CCL25, CDCP1, FGF-21, IL-8, IL-10RB, IL-18, MMP-10, TNFRSF9; all p < 0.05) without interaction by diabetes type." (PMID 39799156, 2025).
ductal carcinoma in situ (1 paper, 2019). "Perou dataset indicated 1.7-fold change in CCL25 (p = 0.034) in Lobular BrCa27 and as per TCGA this change was 1.4 fold (p = 0.015) in ductal carcinoma in situ." (PMID 30850664, 2019).
experimental autoimmune encephalomyelitis (1 paper, 2024). An autoimmune demyelinating disease of the central nervous system that is produced experimentally in animals by the injection of homogenized brain or spinal cord in Freund's adjuvant. "Toll-like receptor 4 (TLR4) plays a role in the pathogenesis of experimental autoimmune encephalomyelitis (EAE) by regulating CCL25/CCR9 expression in response to Th17 infiltration." (PMID 39199524, 2024).
gastroduodenitis (1 paper, 2016). "Further, study is needed to evaluate the role of CCL25 and GM-CSF in the pathogenesis of the different etiologies of gastroduodenitis." (PMID 28018296, 2016). "Further study, using animal model for H. pylori gastroduodenitis is needed to determine the roles of CCL25 and GM-CSF in the pathogenesis of gastroduodenitis." (PMID 28018296, 2016). "The most intriguing observation made in this study was that GM-CSF and CCL25 may play a role in the pathogenesis of gastroduodenitis, and that changes in serum levels of GM-CSF and CCL25 may reflect the host's reaction to disease." (PMID 28018296, 2016). "Additionally, we present the first evidence for a potential role for CCL25 and GM-CSF in the pathogenesis of gastroduodenitis, and that the CCL25/GM-CSF ratio can be utilized to for the discrimination of gastroduodenitis caused by H. pylori from gastroduodenitis due to other causes." (PMID 28018296, 2016). "H. pylori positive and negative juveniles were positioned on either side of controls, suggesting that the CCL25/GM-CSFratio reflects an essential difference in gastroduodenitis pathogenesis with H. pylori positive and negative stomach having distinct forms." (PMID 28018296, 2016). "Further, an intriguing observation was that the CCL25/GM-CSF ratio differed significantly between H. pylori positive and negative children with gastroduodenitis." (PMID 28018296, 2016).
glioma (1 paper, 2022). A benign or malignant brain and spinal cord tumor that arises from glial cells (astrocytes, oligodendrocytes, ependymal cells). "In gliomas with high CASZ1 expression, we found a restricted infiltration level but upregulated chemokines, including CXCL16, CCL22, CCL25, and CXCL2, which could attract DCs and T cells." (PMID 36276925, 2022).
gout (1 paper, 2023). A condition characterized by painful swelling of the joints, which is caused by deposition of urate crystals. "We found two proteins FGF-21 and CCL25 significantly overexpressed in HU patients with gout compared to NU gout and another 8 nominally significant." (PMID 37810213, 2023).
influenza infection (1 paper, 2024). "CCL25, a chemokine ligand for CCR9, has been shown to play both pro- and anti-inflammatory roles in various diseases, while CCL3 and its receptor CCR5 involvement in leukocyte recruitment into the airway to up-regulate antiviral responses in influenza infection." (PMID 39331702, 2024).